Y_RNA (Y RNA )
Gene: Miscellaneous RNA gene on chromosome 2 (32,945,339 to 32,945,451, reverse strand). Ensembl gene ENSG00000206951.
Homologues: Orthologues: chimpanzee Y_RNA (99% identical), macaque Y_RNA (93% identical), guinea pig Y_RNA (85% identical). Paralogues in human: RNY1 (86% identical), Y_RNA (85% identical), RNY1P11 (84% identical), RNY1P8 (84% identical), Y_RNA (84% identical), Y_RNA (83% identical), Y_RNA (82% identical), Y_RNA (81% identical), RNY1P10 (80% identical), Y_RNA (80% identical), RNY1P7 (79% identical), Y_RNA (79% identical), and 96 more.